JMJD6 (jumonji domain containing 6, arginine demethylase and lysine hydroxylase)
Diseases named in the same sentence as JMJD6 in open-access papers (continued):
Sharing a sentence is not in itself a finding about the gene and the disease.
ovarian carcinoma (12 papers, 2017 to 2024). A malignant neoplasm originating from the surface ovarian epithelium. "High expression of JMJD6 is significantly associated with age, clinical stage, pT status and pN status of the ovarian cancer patients." (PMID 31961032, 2020). "The results indicated that high expression of JMJD6 in ovarian cancer was significantly associated with age, clinical stage, pT status, pN status, and relapse." (PMID 31637004, 2019). "JMJD6 inhibition has been revealed to suppress proliferation and induce apoptosis in ovarian cancer cells." (PMID 38166895, 2024). "Consistent results were observed that JMJD6 was widely expressed in tumor stromal cells of multiple cancer types including gastric, liver, colon, lung and ovarian cancer." (PMID 37567973, 2023). "The JMJD6 inhibitor SKLB325 has shown potent anti-ovarian cancer effects in an intraperitoneal xenograft model." (PMID 37218871, 2023). "It is surprising to note that SKLB325, which inhibits the activity of arginine demethylases, JMJD6, has been found to suppress cell proliferation, induce apoptosis, enable antitumor activities, and display effectiveness in the treatment of ovarian cancer." (PMID 37218871, 2023). "Given the potential value of JMJD6 in cancer treatment, researchers have accordingly designed an inhibitor, SKLB325, based on the crystal structure of the jmjC domain of JMJD6, which was demonstrated to possess remarkable antitumor effects in ovarian cancer." (PMID 33634984, 2021). "Inhibition of JMJD6 suppresses cellular proliferation and migration, and promotes apoptosis of ovarian cancer cell lines." (PMID 31961032, 2020). "In the present study, we found that the high expression of JMJD6 in ovarian cancer was correlated with poor prognosis in ovarian cancer." (PMID 31637004, 2019). "JMJD6 was highly and lowly expressed in 90 (61.64%) and 56 (38.36%) of the 146 ovarian cancer patients, respectively, according to the intensity of immunoreaction." (PMID 31637004, 2019). "In our research, JMJD6 protein expression was detected by immunohistochemical staining in a cohort of 146 ovarian cancer specimens, and we analyzed the relationship between JMJD6 protein expression and clinicopathological variables." (PMID 31637004, 2019). "We found that the nuclear staining of JMJD6 varied from low levels to intermediate (b) and strong levels (c) in ovarian cancer tissue." (PMID 31637004, 2019). "In our research, the expression of JMJD6 was detected by tissue microarray immunohistochemical staining, and we found high expression of JMJD6 in ovarian cancer, which was correlated with poor prognosis." (PMID 31637004, 2019). "The expression of JMJD6 protein in 146 ovarian cancer tissue samples was detected by immunohistochemical staining to explore the relationship between the expression of JMJD6 and the clinicopathological characteristics of ovarian cancer patients." (PMID 31637004, 2019). "JMJD6-depletion concomitantly elevated BRD4-S492/494 expression in various ovarian cancer cells." (PMID 37737256, 2023). "JMJD6 is highly expressed in 61.64% of 146 ovarian cancer patients." (PMID 31961032, 2020). "In recent years, JMJD6 has been thought to be related to the occurrence and development of a variety of tumors, including breast cancer, melanoma, oral cancer, glioblastoma, hepatocellular carcinoma, colon cancer, ovarian cancer and neuroglioma." (PMID 33109235, 2020). "In the present study, we demonstrated that JMJD6 may be a marker of poor prognosis in ovarian cancer." (PMID 31637004, 2019). "Altogether, these data showed that expression of JMJD6 may play a role in predicting OS in ovarian cancer." (PMID 31637004, 2019). "We next investigated the prognosis of JMJD6 expression in ovarian cancer." (PMID 31637004, 2019). "However, there is still limited information on the expression of JMJD6 in ovarian cancer." (PMID 31637004, 2019).
ovarian carcinoma (continued). "Furthermore, multivariate Cox regression analysis was used to determine whether the expression of JMJD6 could be an independent predictor for OS or DFS of ovarian cancer." (PMID 31637004, 2019). "Furthermore, we designed inhibitors based on the crystal structure of the jmjC domain of JMJD6 and selected the most active inhibitor, SKLB325, and conducted a study of the antitumor effects of SKLB325 on ovarian cancer in vivo and in vitro." (PMID 31637004, 2019). "Taken together, our findings suggest that JMJD6 may be a marker of poor prognosis in ovarian cancer and that SKLB325 may be a potential candidate drug for the treatment of ovarian cancer." (PMID 31637004, 2019). "In addition, considering the potential value of JMJD6 in cancer therapy, an inhibitor SKLB325 has been designed based on the crystal structure of the JmjC domain of JMJD6, which has shown significant anti-tumor effects in ovarian cancer." (PMID 37488513, 2023). "However, there are no studies reporting the expression of JMJD6 in ovarian cancer, and no JMJD6 inhibitors have been developed and applied to targeted cancer therapy research." (PMID 31637004, 2019). "Furthermore, no JMJD6 inhibitors have been developed and applied to the research of ovarian cancer." (PMID 31637004, 2019). "However, the expression of JMJD6 in ovarian cancer has not been reported." (PMID 31637004, 2019).
prostate carcinoma (12 papers, 2017 to 2025). A carcinoma that arises from epithelial cells of the prostate gland. "The aberrant expression of JMJD6 is associated with progression, prognosis and treatment resistance in multiple tumors such as breast, hepatic, prostate cancer and neuroblastoma." (PMID 37567973, 2023). "Aberrant JMJD6 catalysis is associated with the upregulation of androgen receptor splice variant 7 (AR‐V7), which confers resistance towards antiandrogens used for prostate cancer treatment; JMJD6 is thus a promising cancer target." (PMID 41170613, 2025). "A recent study found that the expression of JMJD6 in prostate cancer was up-regulated with the progression of stage and grade." (PMID 37488513, 2023). "The aberrant expression of JMJD6 has been reported in a wide panel of tumor types such as breast, hepatic, prostate cancer, colorectal cancer and neuroblastoma." (PMID 37567973, 2023). "NMR and MS assays on JMJD6, a prostate cancer target, identify 2‐oxoglutarate competitors, including human drugs and drug candidates, as JMJD6 inhibitors." (PMID 34581506, 2022). "According to our bioinformatic analysis from TCGA database, JMJD6 has upregulated expression in prostate cancer patient samples, and shows co-expression and parallel upregulation with AR-V7." (PMID 33430885, 2021). "During the preparation of this report, a highly relevant publication highlighted the relationship between catalytic function of JMJD6 and the generation of AR-V7 mRNA in advanced prostate cancer." (PMID 33925994, 2021). "We identified regulons (networks of genes similarly regulated) from our preclinical prostate cancer models and further evaluated the top ranked JMJD6 gene related regulated network in three independent clinical patient cohorts." (PMID 33925994, 2021). "Analysing all available prostate cancer datasets in the cBio-portal (n = 22), altered JMJD6 gene was detected in multiple cohorts, with the highest incidence of genetic abnormalities (up to 8%) detected in metastatic tumours." (PMID 33925994, 2021). "Interestingly, JMJD6 was an essential regulator of AR-V7, and increased JMJD6 was correlated with higher levels of AR-V7, castration resistance and shorter survival, JMJD6 knockdown suppressed the growth of prostate cancer cells, AR-V7 levels, and the introduction of U2AF65 to AR pre-mRNA." (PMID 35359945, 2022). "Similarly, another study also verified that the JMJD6/U2AF65/AR-V7 axis may confer castration-resistant prostate cancer development." (PMID 35359945, 2022). "Therefore, JMJD6 is considered in relation to prostate cancer development." (PMID 33430885, 2021).
lung adenocarcinoma (11 papers, 2014 to 2025). A carcinoma that arises from the lung and is characterized by the presence of malignant glandular epithelial cells. "When analyzed for clinical associations between lung adenocarcinoma and JMJD6 expression, the study group with high JMJD6 expression was positively associated with tumor size, pathological grade, and pleural invasion." (PMID 28587176, 2017). "Univariate and multivariate Cox regression studies revealed that JMJD6 expression was associated with decreased overall survival rate and was an independent prognostic factor for overall survival rate and adverse clinical outcome in patients with adenocarcinoma of the lung." (PMID 28587176, 2017). "To identify the role of JMJD6 in lung cancer, we retrieved RNA-seq data of lung adenocarcinoma (LUAD) and lung squamous cell carcinoma (LUSC) patients from TCGA." (PMID 41320721, 2025). "PCAF also acetylates transcriptional factor HOXB9, leading to the suppression of lung adenocarcinoma progression via the targeting of oncogenic protein JMJD6." (PMID 36678613, 2023). "In lung adenocarcinoma, the level of JMJD6 was remarkably increased, high JMJD6 expression was associated with size, grade, pTN status, pleural invasion, and poor prognosis." (PMID 35359945, 2022). "Kaplan–Meier analysis showed that lung adenocarcinoma patients with high JMJD6 expression had a significantly lower overall survival rate compared to those with low JMJD6 expression." (PMID 28587176, 2017). "Furthermore, high-level expression of JMJD6 in human neuroblastoma and lung adenocarcinoma (EAC) independently predicted poor patient prognosis." (PMID 37488513, 2023). "JMJD6 mRNA and protein are significantly increased in human lung adenocarcinoma specimens." (PMID 31961032, 2020). "High expression of JMJD6 predicts unfavorable survival in lung adenocarcinoma." (PMID 24667498, 2014).
neuroblastoma (10 papers, 2019 to 2024). Neuroblastoma (NB) is the most common solid, extracranial childhood tumor. "We noticed that the loss of JMJD6 led to neurite outgrowth, a unique structure of neuroblastoma cells differentiating in vitro." (PMID 38488852, 2024). "Among the genes encoding JmjC domain containing proteins, JMJD6 was the only one that was frequently amplified in neuroblastoma." (PMID 38488852, 2024). "JMJD6 knockout was negatively correlated with the knockout of genes housed at chromosome 1p, which is frequently deleted in high-risk neuroblastoma, and oxidative phosphorylation as well as protein translation." (PMID 38488852, 2024). "Taken together, these data demonstrate that loss of JMJD6 function impedes neuroblastoma cell survival and tumor growth." (PMID 38488852, 2024). "Kaplan–Meier survival analysis showed that high levels of JMJD6 mRNA expression in human neuroblastoma tissues were associated with poor prognosis in the 88 and the 476 neuroblastoma patients of the Versteeg and the Oberthuer datasets, respectively (p < 0.0001)." (PMID 31346162, 2019). "To assess this possibility, we knocked down JMJD6 in neuroblastoma cell lines BE2(C) and SK-N-AS, which express MYCN and MYC, respectively, for RNA-seq analysis." (PMID 38488852, 2024). "To understand the role of JMJD6, we examined the genetic features of JMJD6 in neuroblastoma and other types of cancers." (PMID 38488852, 2024). "Collectively, these data demonstrate that JMJD6 regulates RNA splicing of genes engaged in mitochondrial metabolism, being one of the key mediators of the 17q locus activity in neuroblastoma." (PMID 38488852, 2024). "Researchers has investigated the cytotoxic effects of indisulam on neuroblastoma, which achieves antitumor activity through the regulation of selective splicing of enzymes involved in glutamine metabolism by controlling JMJD6." (PMID 39044280, 2024). "Lastly, we validated that JMJD6 is essential to neuroblastoma growth in MYCN-amplified (BE2C) and MYC-overexpressed (SK-N-AS) xenograft models." (PMID 38488852, 2024). "Knockdown of JMJD6 inhibited the proliferation and survival of neuroblastoma cells and tumor progression in mice." (PMID 37488513, 2023). "We have found positive correlation between JMJD6 and N-Myc/c-Myc expression in human neuroblastoma tissues." (PMID 31346162, 2019). "Alamar blue assays showed that overexpression of JMJD6 partially reversed the reduction in the number of viable neuroblastoma cells after treatment with THZ1 and panobinostat combination therapy." (PMID 31346162, 2019). "The data suggest that high levels of JMJD6 expression due to chromosome 17q21-ter segmental gain contributes to neuroblastoma pathogenesis." (PMID 31346162, 2019). "Two-sided Pearson’s correlation study revealed that JMJD6 mRNA expression positively correlated with N-Myc/c-Myc mRNA expression with a good effect size (R = 0.447) in the 476 neuroblastoma tissues." (PMID 31346162, 2019). "Alamar blue assays showed that forced overexpression of JMJD6 largely reversed the effect of JMJD6 siRNAs in reducing the number of viable neuroblastoma cells." (PMID 31346162, 2019). "Taken together, the data suggest that the JMJD6 gene is commonly gained in human neuroblastoma tissues, and that a high level of JMJD6 expression independently predicts poor patient prognosis." (PMID 31346162, 2019). "Our data therefore demonstrate that THZ1 and panobinostat combination therapy synergistically blocks neuroblastoma progression and induces tumor regression by blocking JMJD6 expression." (PMID 31346162, 2019). "While E2F and Myc are well-known tumorigenic factors, we have confirmed that knocking down JMJD6 considerably reduces neuroblastoma cell proliferation, induces apoptosis, and dramatically reduces clonogenic capacity." (PMID 31346162, 2019).
neuroblastoma (continued). "Knocking down JMJD6 reduces neuroblastoma cell proliferation and survival in vitro and tumor progression in mice, and high levels of JMJD6 expression in human neuroblastoma tissues independently predict poor patient prognosis." (PMID 31346162, 2019). "Our findings therefore identify JMJD6 as a neuroblastoma tumorigenesis factor, and the combination therapy as a treatment strategy." (PMID 31346162, 2019). "Here, the authors are showing that JMJD6, which locates in that region, is a neuroblastoma tumorigenic factor." (PMID 31346162, 2019). "Taken together, the data suggest that JMJD6 is required for neuroblastoma cell proliferation, survival, and tumorigenic capacity." (PMID 31346162, 2019). "Although we have identified a conserved interactome of JMJD6 in neuroblastoma cells, it remains to be determined whether it is neuroblastoma-specific and essential to MYC-driven cancers." (PMID 38488852, 2024). "Our study focused on the understanding of JMJD6 function in neuroblastoma cell lines." (PMID 38488852, 2024). "We then validated the interactions of JMJD6 with splicing factors using immunoprecipitation and western blot, and demonstrated that JMJD6 formed a complex with these RNA binding proteins, including RBM39, a therapeutic target of high-risk neuroblastoma." (PMID 38488852, 2024). "JMJD6 is required for neuroblastoma growth and facilitates MYC-mediated cellular transformation." (PMID 38488852, 2024). "The results showed that loss of JMJD6 greatly reduced the colony numbers in all tested cell lines, demonstrating that JMJD6 is essential to neuroblastoma cells regardless of MYCN amplification." (PMID 38488852, 2024). "We further compared the RNA-seq expression of JMJD6 in 2337 samples across over 20 pediatric cancer subtypes and found that JMJD6 showed the highest expression levels in neuroblastoma, suggesting that JMJD6 might be particularly important in neuroblastoma." (PMID 38488852, 2024). "Our data therefore confirm the critical role of JMJD6 in neuroblastoma tumorigenesis." (PMID 31346162, 2019). "Importantly, chromosome 17q segmental gain and high levels of JMJD6, but not 17q numerical gain or high levels of MXRA7, the gene immediately upstream of JMJD6 at chromosome 17qter, in neuroblastoma tissues correlate with poor patient prognosis." (PMID 31346162, 2019). "In addition, our data demonstrate that JMJD6 overexpression in neuroblastoma tissues predicts poor patient prognosis, independently of other prognostic markers such as MYCN amplification status, age at the time of diagnosis, and disease stage." (PMID 31346162, 2019). "As N-Myc and c-Myc are well known to induce gene transcription by binding to Myc-responsive element E-boxes at target gene promoters, our data suggest that N-Myc and c-Myc overexpression in human neuroblastomas further increases JMJD6 expression, even in JMJD6 gene-gained cells." (PMID 31346162, 2019). "In this study, we have found that the JMJD6 gene is gained in ~80% of human neuroblastoma tissues." (PMID 31346162, 2019). "We have found that the JMJD6 gene is associated with transcriptional super-enhancers in JMJD6 gene-gained neuroblastoma cells, and that treatment with the CDK7 inhibitor THZ1, which specifically targets super-enhancer associated oncogenes, significantly reduces JMJD6, N-Myc, and c-Myc expression." (PMID 31346162, 2019). "Nevertheless, loss of JMJD6 induced an induction of gene signatures related to axon, neuron projection, and Schwann cell differentiation, which is consistent with the induction of neurite outgrowth observed in BE2C cells after JMJD6 knockdown, indicative of neuroblastoma cell differentiation." (PMID 38488852, 2024). "In chromosome 17q-gained neuroblastoma, the JMJD6 gene is over-expressed due to both gene gain and transcriptional super-enhancers, and suppression of super-enhancer activity reduces JMJD6 gene expression, neuroblastoma cell proliferation in vitro and tumor growth in a mouse model." (PMID 38135679, 2023).